AR (androgen receptor)
Diseases named in the same sentence as AR in open-access papers (continued):
Sharing a sentence is not in itself a finding about the gene and the disease.
prostate carcinoma (continued). "The androgen receptor (AR) is a key regulator of prostate growth, promoting glycolysis and anabolic metabolism, and the principal drug target for the treatment of prostate cancer." (PMID 30234009, 2018). "The hormone receptors, such as estrogen receptor alpha and androgen receptor in breast cancer and prostate cancer, are critical to cancer cell proliferation and tumor growth." (PMID 29342868, 2018). "The enhanced expression of TRIM36 due to AR signaling in prostate cancer is considered to be a reasonable explanation for this phenomenon." (PMID 29449534, 2018). "It is possible that the hypoxia/HIF pathways, albeit oncogenic, are secondary to AR in driving prostate cancer." (PMID 30478344, 2018). "Androgen receptor (AR), an important target in the current androgen derivation therapy, plays a critical role in the development and progress of prostate cancer (PCa)." (PMID 30210333, 2018). "The involvement of H2AZ and EZH2 in prostate cancer and the reported down regulation of AR gene by metformin prompted us to further analyze the role of this drug in these two important epigenetic components." (PMID 30651935, 2018). "For example, it has been shown that glucocorticoids regulate AR expression in monkey kidney fibroblast COS-1 cells, while AR signals inhibit GR gene transcription in human prostate cancer cell lines, androgen-dependent LNCaP and castration-resistant C4-2." (PMID 30518063, 2018). "Androgens and androgen receptor (AR) signaling play a predominant role in male sexual development, growth of the prostate gland and progression of prostate cancer to CRPC2." (PMID 31328183, 2018). "Intriguingly, IL-17, AR, and vitamin D3 are therapeutic targets in rheumatoid arthritis and have potential, as a frontline treatment option for advanced prostate cancer and an adjuvant in melanoma management." (PMID 29904382, 2018). "Several studies based on molecular cloning of AR cDNA, suggest that its transcriptional activity is critical for all stages of prostate cancer development and progression." (PMID 31328183, 2018). "Prostate cancer cells express the androgen receptor (AR) and are heavily reliant on androgens for growth and survival." (PMID 29967592, 2018). "Androgen steroid hormones and the androgen receptor (AR) play a key role in the development and progression of prostate cancer, with alternative splicing enabling cancer cells to produce constitutively active ARs11–13." (PMID 30271587, 2018). "For instance, AR-amplified prostate cancer organoids were exquisitely sensitive to the AR inhibitor enzalutamide, while AR-negative prostate cancer organoids responded to this drug in an opposite manner." (PMID 30219074, 2018). "The pro-mitotic protein PLK1 is upregulated in AR-independent prostate cancer cells, and PLK1 inhibitors promote necroptosis." (PMID 29371637, 2018). "Next, we applied transIndel to detect 10 validated large deletions (> 1 kb) within the androgen receptor (AR) gene locus from prostate cancer specimens." (PMID 29673323, 2018). "Androgens have also been shown to be able to regulate the expression of AR coregulators in prostate cancer." (PMID 30416486, 2018). "Ligand-dependent and other molecular interactions of androgen receptor (AR) play a pivotal role in the development of prostate cancer and its progression to lethal forms." (PMID 29921791, 2018). "Especially, isoform switching of kinase gene CDK5 was found in prostate cancer and benign tissues, which suggests its regulatory role in AR phosphorylation via alternative splicing." (PMID 30367578, 2018). "Genistein decreases HDAC6 expression, abrogating Hsp90 activity, and consequently downregulating AR and prostate cancer cell proliferation." (PMID 30627525, 2018). "Few studies have compared prostate cancer myofibroblasts that differ in AR expression or signalling." (PMID 29721186, 2018).
prostate carcinoma (continued). "Androgens are steroid hormones that are involved in sexual differentiation and prostate cancer progression in men, and the androgen receptor (AR) is a clinical target in androgen-dependent and castration-resistant prostate cancer." (PMID 29713287, 2018). "AR is one of the most important factors driving progression of prostate cancer, but its role in breast cancer is less clear." (PMID 29928478, 2018). "It has been reported that protein CDK5 encoded by Isoform1 can phosphorylate AR at its Ser-81 site and therefore activate and stabilize AR to promote prostate cancer cell growth in prostate cancer cell line." (PMID 30367578, 2018). "Androgen receptor (AR), a steroid hormone receptor normally activated by androgens, plays an essential role in prostate cancer (PCa) development, progression, and therapy response." (PMID 30190514, 2018). "This is consistent with the previous studies, though some studies still indicating the positive role of AR in promoting prostate cancer metastasis." (PMID 30200999, 2018). "Overexpressed AR signaling develops resistance of prostate cancers to existing anti-androgen treatments." (PMID 30177619, 2018). "As the androgen receptor (AR) is the main oncogenic driver in prostate cancer, most drugs used for the treatment of this disease are aimed at inhibiting AR activity (Aragon‐Ching, 2014)." (PMID 29437778, 2018). "In men with castrate resistant prostate cancer genomic studies showed a high frequency of AR pathway alterations; this suggests that the tumor cells remain dependent of AR signaling for viability." (PMID 30180883, 2018). "In a similar role, in prostate cancer, androgen receptor (AR) mediates various functions of androgens essential for cell viability, development and invasion in both androgen dependent and independent prostate cancers." (PMID 30323717, 2018). "AR pathway‐targeted therapies provide the greatest clinical benefit for men with castration‐resistant prostate cancer by relieving symptoms and improving survival." (PMID 29348142, 2018). "We report the first high-throughput CETSA (CETSA HT) assay for the determination of intracellular target engagement with AR, measured in disease-relevant cell lines derived from primary human prostate cancers." (PMID 29317749, 2018). "The levels of AR-V mRNA and protein expression relative to AR-FL varies within normal and malignant prostate tissues, CPCs and prostate cancer cell lines." (PMID 30180883, 2018). "Provocatively, it was found that FOXA1 also has the potential to reprogram GATA2 and act as a pioneering effect for both AR and GATA2, suggesting that FOXA1 regulates a transcriptional network that controls AR-mediated gene expression in prostate cancer." (PMID 29888169, 2018). "As such, intratumoral steroidogenesis that takes place in prostate cancer cells has been identified as a castration resistance mechanism where AR is reactivated despite low levels of circulating testosterone." (PMID 30241348, 2018). "A study showed that Prx II knockdown affects to prostate cancer cell growth via AR signaling by presenting the evidence that Prx II inhibits growth only in AR-expressing prostate cancer cells but not in AR-null cells." (PMID 30177619, 2018). "In the present study, we demonstrate the role of RNase L as a suppressor of AR signaling, cell migration and activity of matrix metalloproteinases identifying an unrecognized role of RNase L in prostate cancer." (PMID 28257035, 2017). "Depletion of androgens can suppress the secretion of proteins by AR positive prostate cancer cells, as is seen in secretion of the prostate cancer clinical biomarker prostate specific antigen (PSA)." (PMID 28881726, 2017).
prostate carcinoma (continued). "The emerging role of high-testosterone (T) therapy in prostate cancer makes AR-induced sensitivity to SLC35F2 transported therapeutics clinically relevant." (PMID 28350329, 2017). "Since AR acts by regulating gene expression in prostate cancer, downstream target genes of AR have important functions in this disease and against which novel therapeutic can be directed." (PMID 28859127, 2017). "Previous studies have shown that AR is overexpressed in some human malignancies, such as prostate cancer, breast cancer, hepatocellular carcinoma, and bladder cancer." (PMID 28423563, 2017). "AR T878A was originally identified in the LNCaP prostate cancer cell line while AR F877L was identified using an in vitro screen for resistance mechanisms to anti-androgens." (PMID 28152506, 2017). "Here, we perform a computational prediction and identify a module of mutually exclusive transcriptional drivers, AR, HOXC6 and NKX2-2, which co-dysregulate a core set of metastasis-associated miRNAs in prostate cancer." (PMID 28397780, 2017). "The androgen-androgen receptor (AR) pathway is important for physiological development and pathogenesis of diseases, such as prostate cancer." (PMID 29050220, 2017). "The therapy attempting to target AR signalling was established in decades ago but the treatment of prostate cancer is far from being satisfactory." (PMID 28151478, 2017). "Indeed, expression of CBR3-AS1 and the AR are tightly linked as CBR3-AS1 was initially shown to directly regulate AR expression, and more recently this lncRNA was shown to regulate the AR by protecting it from microRNA (miR-34c and miR-297) mediated suppression in prostate cancer cells." (PMID 28430163, 2017). "Our recent study showing that IU1 significantly decreased the growth of androgen-responsive prostate cancer cells through induction of ubiquitination and degradation of androgen receptor highlights the therapeutic role of USP14 inhibitors." (PMID 29039082, 2017). "AR pre-mRNA splicing changes thus enable prostate cancer cells to proliferate during androgen deprivation therapy in reduced circulating androgen concentrations." (PMID 28382513, 2017). "Hydroxyflutamide (HF), an active metabolite of the first generation antiandrogen flutamide, was used in clinic to treat prostate cancer targeting androgen receptor (AR)." (PMID 28832499, 2017). "Expression of the androgen receptor (AR), the single most important regulator of prostate cancer growth, was assessed throughout prostate carcinogenesis by IHC." (PMID 29212195, 2017). "Depleting androgen or inhibiting AR transcriptional activity has been proven to be effective in prostate cancer treatment." (PMID 28903374, 2017). "In particular, we would like to focus on miRNAs regulated by AR or those regulating AR activity, because enhanced AR activity is important for the progression of prostate cancer." (PMID 28783103, 2017). "AR is generally considered as a transcriptional activator, although in prostate cancer AR can also repress gene expression, and thus we believe it is more likely that AR functions through the latter mechanism to influence circRNA expression in HCC." (PMID 29144509, 2017). "Cyproterone acetate (CPA), a synthetic steroid was initially utilized for prostate cancer treatment because of its ability to block the androgen receptor (AR) and reduce serum testosterone levels." (PMID 28270124, 2017). "In prostate cancer (PC), androgen receptor (AR) binding sites to chromatin have been used to inform functional annotations of SNPs." (PMID 28359301, 2017). "AR-driven complex transcriptional programs have previously been used as a starting point to identify prostate cancer-specific metabolic vulnerabilities." (PMID 28415728, 2017). "Substantial evidences had showed androgen receptor (AR) and its signaling pathway played pivotal roles in development and progression of prostate cancer." (PMID 28771526, 2017).
prostate carcinoma (continued). "Nuclear receptors are amongst the most successful therapeutic targets in oncology, with small molecule inhibitors of estrogen receptor (ER) and androgen receptor (AR) improving survival in breast and prostate cancers." (PMID 29143738, 2017). "Our previous analyses suggested that Aurora kinase A (AURKA) is regulated by androgens in prostate cancer cells that express high levels of AR." (PMID 29269934, 2017). "Several studies demonstrate the importance of microtubules and actin cytoskeleton in shuttling of AR from cytoplasm to the nucleus in cell lines and in clinical samples of prostate cancers." (PMID 28257035, 2017). "AR activity can be dichotomous in action by promoting prostate cancer growth under normal circumstances and retarding its growth when overstimulated with excessive androgens." (PMID 28350329, 2017). "It is well known that the AR-regulated transcriptional program plays a vital role in driving progression of prostate cancer." (PMID 28420185, 2017). "We have previously reported that USP14 regulates prostate cancer proliferation by deubiquitinating and stabilizing androgen receptor." (PMID 28968984, 2017). "One commonly used endogenous PPARγ ligand, 15dPGJ2, does reduce AR activation in LNCaP and VCaP prostate cancer cells." (PMID 29181019, 2017). "Only in some prostate cancer cells can LSD1 bind to androgen receptor in a ligand-dependent manner to remove the methyl groups from mono- and dimethylation of H3K9 to activate gene expression." (PMID 28121627, 2017). "On the other hand, the AR modulates the expression of some microRNAs which are involved in prostate cancer cell proliferation." (PMID 28486411, 2017). "The reliance of prostate cancer on AR signaling has led to the development of potent androgen pathway targeted treatments." (PMID 28420128, 2017). "The cross-regulation of PKD1 by androgen/AR places PKD1 in the AR-induced signaling network, which is critical to prostate cancer progression." (PMID 28077787, 2017). "At present, androgen receptor antagonists, such as bicalutamide and flutamide, are used as main hormone therapies for prostate cancer." (PMID 28293633, 2017). "The current therapy of prostate cancer is mainly based on androgen receptor activity at almost all the stages of prostate cancer." (PMID 28272371, 2017). "Although the underlying mechanisms driving prostate carcinogenesis remain elusive, it is widely accepted that prostate cancer cell growth and survival is exquisitely dependent upon activation of the androgen receptor (AR) by androgens." (PMID 27902483, 2017). "Lut inhibited cell proliferation and induced apoptosis in LNCaP human prostate cancer cells by mediated AR downregulation." (PMID 28588640, 2017). "CPA represents the first generation of AR blockers for prostate cancer androgen deprivation therapy." (PMID 28270124, 2017). "To date, the mechanisms facilitating resistance to androgen-deprivation and anti-AR therapies in prostate cancer remain poorly understood." (PMID 28596572, 2017). "Development and maintenance of the prostate requires androgens and AR dysregulation plays an important role in the development of prostate cancer." (PMID 29108248, 2017). "When ADT is initiated, reduction in circulating testosterone reduces AR activity in prostate cancer cells and, correspondingly, the serum PSA level decreases." (PMID 28604629, 2017). "The androgen receptor (AR) is a member of the nuclear receptor superfamily of transcription factors and is central to prostate cancer (PCa) progression." (PMID 28038451, 2017). "Prostate cancer biology is initially dominated by activity of the androgen receptor (AR), and androgen deprivation therapy (ADT) is the backbone of therapy for those with metastatic prostate cancer." (PMID 28228136, 2017). "AR has therefore become an even more attractive therapeutic target in aggressive and disseminated prostate cancer." (PMID 28570625, 2017).
prostate carcinoma (continued). "Some reports in prostate cancer have identified miRs in androgen receptor (AR) signaling, such as miR-21, owing to AR binding on the defined promoter, was directly up-regulated by AR." (PMID 28422730, 2017). "The primary role of AR in prostate cancer (PCa) is to regulate the expression of genes that are essential for prostate tumorigenesis." (PMID 28252832, 2017). "The transcriptional function of the androgen receptor (AR) is essential for the genesis and development of prostate cancer." (PMID 28474232, 2017). "The use of HT in prostate cancer treatment is controversial because it prevents androgen receptor expression in human prostate cancer cells; hence, they do not respond to hormone therapy." (PMID 28580312, 2017). "All cell models used expressed the AR full length (i.e., 110 kDa), while prostate cancer cells were positive for several AR splicing forms (e.g., ARΔLBD or AR 75–80 kDa)." (PMID 28239427, 2017). "Expression of ARv7 is controlled by the transcription factors Myc (Myc also controls the expression of full-length AR) and NFκβ2, both of which increase expression in prostate cancer." (PMID 28382513, 2017). "5α-reductase can convert testosterone into dihydrotestoterone (DHT), which subsequently binds to the androgen receptor (AR) (a ligand-dependent transcriptional factor), contributing to prostate cancer development and progression." (PMID 29200992, 2017). "In this study, we present the novel findings demonstrating that PKD1 was repressed by androgen/AR at the mRNA and protein levels in androgen-sensitive prostate cancer cells, identifying PKD1 as a novel androgen-repressed gene." (PMID 28077787, 2017). "A recent study has suggested that the PPARγ antagonist GW9662 also regulates AR signaling within AR-positive, castration-sensitive prostate cancers." (PMID 29181019, 2017). "The murine TRAMPC1 cells are a prostate cancer cell model that expresses AR and has been recently used for enzalutamide studies." (PMID 28915573, 2017). "Meanwhile, reduction in 5-hmC by miR-29a/b activated prostate cancer-related key pathways such as mammalian target of rapamycin (mTOR) and AR, indicating significant oncogenic roles of miR-29 in prostate cancer progression." (PMID 28783103, 2017). "It has been reported that Kdm3a can work with androgen receptor to upregulate c-Myc expression in prostate cancer cells." (PMID 29156681, 2017). "The presence of AR-FL and ARVs protein and/or mRNA has been detected in castration-resistant prostate cancer cells." (PMID 29181019, 2017). "As a result there is still a desire to identify novel treatments for prostate cancer that interfere with AR signaling, especially those compounds that target AR regions outside of the LBD." (PMID 29181019, 2017). "Another member of the CDK family, CDK6, also stimulates AR transcriptional activity in prostate cancer cells." (PMID 28262798, 2017). "Androgen receptor (AR) mediates initiation and progression of prostate cancer (PCa); AR-driven transcription is activated by binding of androgens to the ligand-binding domain (LBD) of AR." (PMID 28977932, 2017). "Whilst FOXA1 represses AR binding to DNA, GATA2 positively collaborates with the AR in androgen-mediated gene expression in prostate cancer." (PMID 28264478, 2017). "We concluded that miR-34b and AR play a pivotal role in the treatment of aggressive African-American prostate cancers." (PMID 28039468, 2017). "The role of AR in the development and progression of prostate cancer has increased interest in this nuclear receptor." (PMID 28039468, 2017). "To date, published reports have described the effects of endogenous PPARγ ligands on AR signaling only within AR-positive, castration-sensitive prostate cancer cells." (PMID 29181019, 2017).